EGFR (epidermal growth factor receptor)
Diseases named in the same sentence as EGFR in open-access papers (continued):
Sharing a sentence is not in itself a finding about the gene and the disease.
tumor (continued). "EGFR protein expression evaluated with 31G7, scored with method (B) and 2.1E1 scored with method (A) showed a significant association with tumor differentiation (p = 0.041 and p = 0.029)." (PMID 25227424, 2014). "The concordance of EGFR mutations in primary tumor and metastases is 94%, and that for mutation ratios is 84%." (PMID 24398248, 2014). "Low mutation rate and low availability of tumour samples limited the sample size for most of the efficacy analyses of erlotinib or gefitinib in patients with EGFR mutation-positive tumours." (PMID 25100284, 2014). "Of the 23 patients that were EGFR-mutation positive in plasma DNA, 6 were positive in the plasma only, and of the 28 patients that were EGFR mutation positive in tumour DNA, 11 were mutation positive in the tumour only." (PMID 24773774, 2014). "The superiority of EGFR-TKIs in ORR and PFS for EGFR-mutated patients indicated its specific efficacy in suppressing the tumor cells that were driven by the EGFR pathway." (PMID 24533047, 2014). "The mean tumor diameter was smaller in patients with EGFR mutations (2.68 ± 0.92 cm) than in those with wild-type EGFR (3.35 ± 1.71 cm; P < 0.001)." (PMID 25152277, 2014). "Afatinib retains inhibitory effects on signal transduction and in vitro and in vivo cancer cell growth in tumours resistant to reversible EGFR inhibitors, such as those exhibiting the T790M mutations." (PMID 24643470, 2014). "Previous studies have shown that up-regulation of EGFR is associated with high tumor grade and worse prognosis." (PMID 25909813, 2014). "In Caucasians, EGFR molecular status at various tumor sites remains to be examined in standard testing conditions to validate EGFR molecular testing as a diagnostic tool." (PMID 24885034, 2014). "Overexpression and/or increased activity of EGFR are the key characteristics of human tumors and are frequently linked to more aggressive tumor behavior, including increased proliferation, metastasis, and therapeutic resistance." (PMID 25063218, 2014). "First, protein expression of Aurora kinase A / B and EGFR and Aurora kinase A polymorphism were studied in tumour samples." (PMID 24980817, 2014). "The most commonly observed mutation of EGFR in human neoplasms is variant III (EGFRvIII), contributing to increased tumorogenicity in primary and secondary brain tumors." (PMID 25268164, 2014). "Among the 50 subjects, only 3 (6%) had different test results for EGFR mutations in primary tumor and metastases, however, the difference was insignificant (P = 0.242) as analyzed by Fisher’s exact test." (PMID 24398248, 2014). "Although a substantial proportion of patients with EGFR mutated tumours develop BM, the prevalence and the best treatment options for progression to the central nervous system (CNS) have not yet been finally determined." (PMID 24991207, 2014). "Of these patients, 130 patients have been genotyped for EGFR mutation status in initial tumor tissue specimens: 91 (70%) patients harbored sensitizing EGFR mutation and 39 (30%) carried the wild-type EGFR gene." (PMID 25405807, 2014). "A few years later, somatic mutations in the EGFR gene were discovered in these highly responsive tumours." (PMID 25264519, 2014). "In 4 cases (13%) double or multiple EGFR mutations were found by NGS in CTCs obtained from patients carrying a single EGFR mutation, detected by Sanger sequencing, in the corresponding tumor biopsy." (PMID 25137181, 2014). "Histology and mutation testing revealed that the tumor was a wild-type EGFR adenocarcinoma (thyroid transcription factor-1 positive)." (PMID 24661457, 2014). "Among 199 advanced adenocarcinoma patients, 24/199 (12%) were EGFR-mutation positive in plasma and 28/196 (14%) were EGFR-mutation positive in tumour DNA." (PMID 24773774, 2014).
tumor (continued). "Monoclonal antibody (mAb) recognizes a unique part of the antigen specifically, e.g. tumor associated antigens like EGFR or HER-2, and these mAbs have been widely used as standard treatment in clinical trails." (PMID 25424625, 2014). "A number of authors have examined the association between the efficacy of EGFR-TKIs and patient demographics, including gender, tumor histology, smoking history and ECOG-PS." (PMID 25364452, 2014). "In NSCLC patients with tumours displaying EGFR mutations, EGFR-TKIs have proven to be a very effective treatment option." (PMID 24643470, 2014). "Recent analysis of TCGA RNA-seq data revealed that multiple EGFR deletion and point mutations were often expressed in the same tumor at different allelic frequencies." (PMID 24292886, 2014). "Blood samples were collected from 37 patients enrolled in the TRIGGER study, a prospective phase II multi-center trial of erlotinib treatment in advanced NSCLC patients with activating EGFR mutations in tumor tissue." (PMID 25137181, 2014). "In summary, both PIK3CA exon 20 mutations and loss of PTEN expression are promising predictors of tumor suitability for anti-EGFR therapies." (PMID 24811491, 2014). "In our study, a total of 109 cases (39 %) with primary tumor tissues or lymph node samples underwent EGFR mutation detection." (PMID 25098700, 2014). "This concept must be coupled with the awareness that the same molecular defects are characteristic for different tumour histotypes, like, for example, EGFR mutations for lung and colon, and PI3K mutations for colon and breast carcinomas." (PMID 25624877, 2014). "Owing to the strong tumor-promoting effect of EGFR mutation and EGFR overexpression, specific small molecule inhibitors directly targeting EGFR are being developed." (PMID 24662070, 2014). "The tumor response rates of gefitinib in NSCLC patients with EGFR mutation were similar: 83% in optimal study compared with 62% in WJTOG3405, 74% in NEJ002, and 71% in IPASS." (PMID 25058005, 2014). "Recently, we found that patients characterised by elevated EGFR and elevated AurkA protein expression in tumour tissue represent a risk group with a poor disease-free survival." (PMID 24980817, 2014). "We were able to detect EGFR DelEx19-mutated CTC prior to therapy in all patients with EGFR mutational status known from tumor biopsies that were assessed." (PMID 24465542, 2014). "According to the CAP/IASCL/AMP molecular testing guidelines, EGFR mutation tests should be able to detect mutations in specimens with at least 50%, but ideally 10% tumor-cell content." (PMID 25538894, 2014). "On the other hand, EGFR mutations were found through all histological subtypes in each tumor consistent with the driver status of this mutation." (PMID 24742923, 2014). "Gatekeeper mutations, the T790M mutation in EGFR associated with resistance to gefitinib, are common mechanisms by which tumor cells acquire resistance to molecularly targeted drugs." (PMID 24939055, 2014). "EGFR is a member of the HER family associated with multiple downstream cell signalling pathways leading to adverse clinical outcomes including tumour growth and metastasis." (PMID 24392136, 2014). "Several studies in adults with GBM suggested that specific tumor markers are associated with a better response to small-molecule inhibitors of EGFR, including erlotinib." (PMID 24744992, 2014). "Activation of EGFR is important for tumor survival and growth and is associated with poor clinical outcome in different malignancies." (PMID 24744992, 2014). "With respect to tumour progression, we wish to point out that EGFR overexpression only occurs in p27Kip1-deficient metastatic T24T cells, but not in the parental T24 cells which express p27Kip1 and are incapable of metastasizing." (PMID 25121353, 2014). "ERBB2 is a member of the epidermal growth factor receptor (EGFR) family that is associated with increased proliferation of tumor cells." (PMID 24926380, 2014).
tumor (continued). "While four out of four mice with the L858R genotype exhibited a complete response to afatinib, six out of seven with the double-mutated EGFR exhibited minor tumour regressions (stable disease) and one progressive disease." (PMID 24643470, 2014). "Statistical analysis of the present results, revealed a significant association between the EGFR mutation and the stage of the tumor." (PMID 23403410, 2013). "In the remaining mutated sample, we observed a slight increase (×1.1) of EGFR expression in tumor by comparison to normal tissue." (PMID 23565769, 2013). "Among 1,217 patients enrolled, an EGFR mutation test (amplification mutation refractory system) was performed on tumor samples from 437 patients (36 %)." (PMID 23361373, 2013). "Recent research has found many other roles that MMP2 plays in tumor progression: MMP2 is linked to EGFR and integrin signaling, which lead to cell migration, and the switch to an angiogenic phenotype in an animal model (Epithelial–Mesenchymal Transition)." (PMID 23936390, 2013). "A single KRAS or EGFR mutation analysis was performed in the tumor samples of 18 and 5 patients, respectively." (PMID 23922984, 2013). "Methods to test EGFR or other mutations in specimens with unfavorable tumor cell content need to be very sensitive." (PMID 24376723, 2013). "Several radiolabeled quinazoline derivatives that have high inhibitory potency against EGFR-TK have been studied for diagnostic tumor imaging." (PMID 23494210, 2013). "This is of special interest, since overexpression of EGFR has been associated with tumor development and poor prognosis in NSCLC and novel inhibitors of this signaling pathway such as cetuximab, erlotinib and gefitinib are of increasing clinical importance." (PMID 22923191, 2013). "The administration of CIK cells directed by the EGFR/CD3 BsAb caused a mean tumor reduction of 69.8%, which was higher than those of other groups (P<0.05)." (PMID 23833649, 2013). "Inhibition of EGFR by different approaches causes increased apoptosis and sensitizes tumor cells to radiation therapy and chemical therapy." (PMID 24314030, 2013). "Overall 13(13/41, 31.7%) cases of wild type EGFR tumor by direct sequencing were identified as having mutation when tested either PNA-LNA PCR clamp or Ion Torrent PGM." (PMID 24376508, 2013). "Our study provides evidence that EGFR dysregulation is associated with tumor progression from dysplasia to full-blown cancer and stimulates invasiveness and is indicative of poor prognosis." (PMID 24303437, 2013). "In summary, in the present study we found that EGFR expression was associated with tumor invasion, lymph node status, number of lymph node metastases, and UICC TNM staging in ESCC patients." (PMID 24131756, 2013). "Out of four tumor samples with EGFR mutations, three were adenocarcinomas and the remaining one was NSCLC with unidentified histology." (PMID 23403410, 2013). "Evaluation of primary tumours revealed EGFR mutations identical to those identified in corresponding metastases in two patients (one case of — one delE746-A750 in exon 19 and one case of L858R substitution in exon 21)." (PMID 23892415, 2013). "Several studies supported the occurrence of MASI in EGFR-mutated tumor cells, and this phenomenon is associated with increased mutant allele transcriptional activity." (PMID 23418425, 2013). "In summary, there is a growing body of evidence to suggest that EGFR inhibitor-induced KRAS mutations that associates with tumor recurrence." (PMID 24304820, 2013). "The real-time PCR method allowed detection of an EGFR c.2582T>A (L861Q) mutation in cytological material with the number of tumor cells ranging from 1,000 to 5,000 (QS=C3+, PTS=95%), obtained using BAC/CT (Fig. 1III)." (PMID 23817662, 2013). "EGFR has been shown to be associated with tumor proliferation and growth, Bcl-2 inhibits tumor apoptosis and MMP-9 and MMP-2 play an indispensable role in tumor invasion and metastasis." (PMID 23420470, 2013).
tumor (continued). "In Europe 50% to 70% of EGFR mutation analyses are performed on bronchial biopsy samples that usually contain a percentage of tumor cells that is lower than 50%." (PMID 24364033, 2013). "Incidence and relative risk of FAEs with EGFR-MoAbs according to tumor types, EGFR-MoAbs and phases of trials." (PMID 24312376, 2013). "EGFR immunoreactivity associated with tumour grade; positivity was detected more often in highly and moderately differentiated than in undifferentiated tumours (p = 0.040)." (PMID 24204699, 2013). "Based on these and other studies, the American Society of Clinical Oncology recommended that patients who are candidates for anti-EGFR therapy should have their tumour tested for KRAS mutation." (PMID 23356214, 2013). "They suggested that either EGFR tyrosine kinase inhibitor or AKT inhibitor abrogated radiation-induced DNA-PKcs phosphorylation at Thr2609 in K-RAS mutated tumor cells." (PMID 23976954, 2013). "Considering with mutant allele specific imbalance of oncogenes in tumor cells harboring gene mutation, copy number gain of EGFR usually occurred in the cells with an EGFR mutation." (PMID 23557218, 2013). "In one additional case the R831H mutation associated with treatment resistance was identified in an EGFR wild type tumor after Sanger sequencing." (PMID 24376723, 2013). "Collectively, these results suggest that loss of expression of IGFBPs in tumour cells treated with EGFR-TKIs results in the activation of IGF1R signalling, which in turn mediates resistance to EGFR antagonists." (PMID 24339922, 2013). "The hyperactivity of Ras pathway is linked to tumor resistance to the approved EGFR antibody therapy." (PMID 23470485, 2013). "Of the patients with plasma EGFR mutations, mutations of identical exon site were detected in the matched tumor tissues." (PMID 23927790, 2013). "One EGFR mutation in exon 21 was detected in cytological material that qualified for the C3 group with >1,000 tumor cells." (PMID 23817662, 2013). "A phase III, open-label study demonstrated the presence in the tumor of a mutation of the EGFR gene is a strong predictor of a better outcome with gefitinib." (PMID 27234384, 2013). "Mutational analysis of EGFR by NGS overcomes the issue of limited tumor amounts because it is highly sensitive." (PMID 24376723, 2013). "The findings of the present study suggest that EGFR mutations are detected in DNA isolated from heterogeneous cytological material containing ≥1,001 tumor cells." (PMID 23817662, 2013). "Does the cellular reprogramming event following oncogene expression in BCCs play a causal role during tumor initiation and what is the contribution of the EGFR-Ras-Raf pathway to it?" (PMID 24071938, 2013). "We explored tumor biopsy quality offered for mutation testing, different mutations distribution, and outcome with EGFR TKI." (PMID 23922984, 2013). "Direct inhibition of apoptosis and an EGFR-associated signaling have been characterized as molecular mechanisms of PGE2-induced tumor growth." (PMID 22923191, 2013). "The results demonstrated that the nonspecific binding of the radiotracer was washed out rapidly and caused increased tumor-to-background ratio due to the irreversible and selective bindings to active state of EGFR kinase." (PMID 23956990, 2013). "Tumor samples are often screened for the presence of this mutation considering its interference with the efficiency of anti EGFR cancer drugs." (PMID 23951046, 2013). "EGFR gene mutations were identified in 21 primary tumours and 26 lymph node metastases, with mutations in primary tumours confirmed in metastases in all cases." (PMID 23892415, 2013). "In 5 patients, 2 different EGFR mutations coincided in the same tumor tissue resulting in a total of 43 mutations." (PMID 23922984, 2013). "Gefitinib anti-tumor efficacy in these patient-derived NSCLC xenografts containing EGFR and KRAS mutation was consistent with the reported results from previous clinical trials." (PMID 23842453, 2013).
tumor (continued). "The expression of annexin A6 (AnxA6) in AnxA6-deficient non-invasive tumor cells has been shown to terminate epidermal growth factor receptor (EGFR) activation and downstream signaling." (PMID 24354805, 2013). "EGFR plays a crucial role in cellular functions implicated in cancer development and is reported to be increased in tumor cells at tumor progression." (PMID 24171795, 2013). "The sensitivity of our assays allowed us to detect EGFR mutations in samples poor (<10%) in tumor cells." (PMID 23934203, 2013). "We then screened 179 patients with CRC for somatic mutations of the EGFR polyA repeats, by comparing, for each patient, the PCR profile obtained from tumor to that from paired non malignant tissue." (PMID 23565769, 2013). "In CRC, outgrowth of tumour subpopulations harboring mutations in components of the EGFR pathway is strongly associated with acquired resistance to cetuximab." (PMID 24152305, 2013). "Among studies of a TKI alone as 1st, 2nd, 3rd line treatment or maintenance therapy, EGFR mutation was identified most frequently and consistently as a predictor of tumor response, and survival outcome." (PMID 24252457, 2013). "The signature features the cancer hallmark EGFR and genes involved in cell adhesion cell migration, cell invasion, tumor growth and tumor progression." (PMID 23590835, 2013). "Significant associations have been found between the level of EGFR expression and some clinicopathological characteristics, including tumor differentiation, tumor stage, lymph node status, and UICC TNM stages." (PMID 24131756, 2013). "Our analysis of this dataset revealed that both HBEGF and the monocytic marker CD64 are predominantly expressed in the stromal compartment, suggesting that tumor-associated mononuclear cells express this EGFR agonist." (PMID 23597096, 2013). "For example, in animal models the phosphorylation status of the EV-associated and tumor cell-derived EGFR (P-EGFR) can be detected in plasma using a simple ELISA assay." (PMID 23508692, 2013). "Accordingly, our present results in human tumor tissue displayed that increased COX-2 (74 kDa) was associated with low EGFR and vice versa." (PMID 24171795, 2013). "Xenograft model L030, with a KRAS mutation and EGFR wild type gene, showed a minor response to gefitinib treatment (25% tumor growth inhibition (TGI))." (PMID 23842453, 2013). "Anti-tumor efficacy studies using gefitinib demonstrated that the EGFR activating mutation model had superior sensitivity and that the KRAS mutation models were resistant to gefitinib." (PMID 23842453, 2013). "EGFR expression or activation is increased in many colonic precancerous lesions and tumours and is implicated in numerous animal models of gastrointestinal tumourigenesis." (PMID 23457600, 2013). "But EGFR overexpression was associated with tumor stage, with the percentage of patients with EGFR overexpression was higher in TNM stage IV than in stages I/II/III CRCs (33% versus 12% respectively, P = 0.023) (data not shown)." (PMID 23865079, 2013). "Epidermal growth factor receptor (EGFR)-activating mutations are major determinants in predicting the tumor response to EGFR tyrosine kinase inhibitors in non-small cell lung cancer (NSCLC)." (PMID 23927790, 2013). "The eight-gene signature features the cancer hallmark epidermal growth factor receptor (EGFR) and genes involved in cell adhesion, migration, invasion, tumor growth and progression." (PMID 23590835, 2013). "Since inhibition of EGFR by specific blocking agents causes growth inhibition in in vitro and in vivo tumor models, this justified the initial development of TKI inhibitors gefitinib and eroltinib." (PMID 23896512, 2013). "In other words, high levels of EGF or the activation of EGF/EGFR pathway had been found to significantly associate with tumor initiation and proliferation." (PMID 23825635, 2013).